RB1 (RB transcriptional corepressor 1)
Diseases named in the same sentence as RB1 in open-access papers (continued):
Sharing a sentence is not in itself a finding about the gene and the disease.
cancer (continued). "Additionally, previous studies reported that ESCC-associated proteins, including PCNA, SLC7A5, CTTN, RB1, EGFR, TP63, and PRMT1, exhibited increased expression in S-III; among these proteins, SLC7A5 and EGFR were FDA-approved drug targets for cancer treatment." (PMID 38652547, 2024). "The intricate interactions between RB1 and cellular pathways emphasize its integral role in maintaining genomic stability and curbing aberrant cell growth, positioning it as a prime target for cancer research and therapeutic interventions." (PMID 38672640, 2024). "The cancer-specific NFYC-AS1 upregulation, which can be partly explained by transcriptional activation by NF-Y or E2Fs as a consequence of RB1 mutations, may indeed exacerbate cell proliferation by facilitating mitotic progression." (PMID 38467619, 2024). "Moreover, the RB1 expression level is indicative of adverse outcomes in cancer patients, which highlights a potential for clinical applications." (PMID 39595122, 2024). "Taken together, the ProstaMine results and results from other cancer types suggest that targeted inhibition of GLI1 or the SHH-GLI1 pathway may reduce the aggressiveness of NKX3-1-loss and RB1-loss PCa." (PMID 38751776, 2024). "We conducted a comprehensive evaluation in the genetics department, with no hereditary history of cancer or relevant pathological background, and initiated a cytogenomic approach in search of germline RB1 gene variants." (PMID 39596402, 2024). "There is an inverse relationship between the expression of the P16 and RB1 genes in cancer cells." (PMID 39351198, 2024). "Given the intricate network of pathways affected by RB1 deficiency and the emerging understanding of downstream effectors, future research could focus on elucidating the crosstalk between RB1 and other key regulatory molecules in cancer cells." (PMID 38672640, 2024). "RB1 is essential for CDK4 inhibitors to inhibit cancer cell proliferation." (PMID 39351198, 2024). "Although RB1 has been reported as a gene without a mutation hotspot, it has been stated that the RbAB pocket domain is rich in cancer-associated missense mutations and sites where a cytosine nucleotide is followed by a guanine nucleotide (CpG)." (PMID 38001596, 2023). "Whole‐genome sequencing revealed inactivation in the second allele of the RB1 gene with no other cancer gene aberrations." (PMID 36177499, 2023). "Importantly, we found that depleting RB in RB1-intact cancer cell lines from a range of histological origins, including the lung (A549), liver (HepG2), and breast (MCF7), also sensitized them to ferroptosis induction." (PMID 36928314, 2023). "As the functions of PARPis are to interfere with DNA repair and induce cell death in cancer cells, we posited that RB1 might affect cancer cell responses to PARPis by disrupting DNA damage repair." (PMID 37937640, 2023).
cancer (continued). "Despite this body of knowledge of RB1 mutational contributions to RB, none of it is used to improve the care we provide to these young cancer patients." (PMID 37239954, 2023). "While RB is considered a canonical cancer, having the first molecularly described tumor suppressor gene (RB1), surprisingly, very little is known about the molecular basis underlying the intraocular behavior of this cancer and the varying mechanisms of treatment resistance." (PMID 37239954, 2023). "Furthermore, these findings provide a molecular mechanism explaining the correlation between ferroptosis and treatment-refractory cancer, wherein RB1 is often lost." (PMID 37183818, 2023). "Although a previous study suggests RB1 loss is highly enriched in YAPoff small-cell/neuro/NE cancer lineages, the absence of RB1 mutation in neuroblastoma suggests the existence of an Rb-independent mechanism for YAP inactivation in neuroblastoma." (PMID 37255415, 2023). "This cancer is predominately driven by biallelic inactivation of the RB1 gene through either a copy number alteration (CNA) and/or single nucleotide variants (SNVs) that negate RB1 protein function." (PMID 37239954, 2023). "Patients with germline RB1 alterations who underwent radiotherapy have twice the risk of developing secondary cancers compared with patients who did not receive radiotherapy." (PMID 35406801, 2022). "In particular, decreased PLP levels may increase cancer susceptibility by stimulating LOH when a muted copy of a tumor suppressor gene, such as BRCA1/2 or Rb1 is inherited in the germline." (PMID 35682766, 2022). "Two of the individual CTCs (CTC1 and CTC2) and the CTC pool had homogenous copy-number profiles, and included amplification on 1q and 8q (MYC), 11q (CCND1, FGF3, FGF4) and allelic loss of regions including several cancer genes on 3p (BAP1), 13q(RB1, BRCA2) and 17p (MAP2K4)." (PMID 36088510, 2022). "Finally, yet importantly, some functions of Rb1 can be appreciated only in the context of the cancer microenvironment and interaction with immune cells." (PMID 35267571, 2022). "The retinoblastoma protein family consists of three proteins (pRB, p107 and p130; also known as RB1, Retinoblastoma-like 1 and Retinoblastoma-like 2 (RBL1-2), respectively) that share significant homology, yet only pRb is found frequently mutated in cancer." (PMID 35663332, 2022). "Many of these associations group into well-known cancer pathways such as NFE2L2, RB1, and MAPK." (PMID 35382456, 2022). "Deletion of Rb1 in surfactant protein C expressing alveolar type 2 cells causes lung hyperplasia and defects in epithelial differentiation, but not cancer." (PMID 35368709, 2022). "The broader expression of RB1 throughout the cell cycle foreshadows its broader impact on cancer." (PMID 35368709, 2022).
cancer (continued). "Activation of E2Fs has been identified virtually in all human cancers and is commonly accompanied by complex dysfunction of their upstream regulators, like inactivation of RB Transcriptional Corepressor 1 (RB1), overexpression of CDKs, or the invalidation of the CDK inhibitors." (PMID 35924788, 2022). "Furthermore, 16 of the associations group into three well-known cancer pathways (NFE2L2, RB1, and MAPK)." (PMID 35382456, 2022). "Furthermore, overexpression of RB1 interfered with the regulation of cell cycle, playing a critical role in the occurrence and development of cancer." (PMID 35299734, 2022). "Retinoblastoma transcriptional corepressor 1 (RB1) and breast cancer 2 (BRCA2) exist close to each other in the same chromosome, and the significance of their concurrent loss has become a hot topic in the field of cancer research." (PMID 35725469, 2022). "The RB1 tumor suppressor gene, discovered and isolated more than 30 years ago, has been the subject of extensive study due to its prominent role in cancer." (PMID 35368709, 2022). "In addition, the most relevant biological process related to RB “aberrant regulation of mitotic G1/S transition in cancer due to RB1 defects” was also enriched for target mRNAs in the network." (PMID 36077715, 2022). "In RB1/p107 and RB1/p130 models, some cancer cells were positive to Müller glial cell markers." (PMID 36230849, 2022). "In conclusion, we identified several small molecule inhibitors that exhibit a selective response in RB1-deficient human cancer cell lines and suggest that TAK-243 might be easily repurposed for the treatment of RB1-deficient cancers in a clinical setting." (PMID 33591981, 2021). "The acceleration of cell cycle progression following RB1 inactivation may provide further exploitable vulnerabilities in cancer therapy." (PMID 34359636, 2021). "In cancer cells, RB is found to be frequently inactive, either because of direct genetic and epigenetic inactivation of the RB gene (also known as RB1) but more frequently by alterations that result in increased activity of the RB kinases Cyclin D-CDK4/6 and Cyclin E-CDK2." (PMID 34879057, 2021). "RB1 is inactivated in a wide range of cancers, including lung ADC and SqCC." (PMID 33407425, 2021). "Besides, it has been found that two other gradients of ginsenoside, called Rb1 and Rg1, can be loaded by CNTs and inhibit cancer development." (PMID 34111025, 2021). "Combined with their genetic analyses in a Drosophila model, the authors identify key metabolic pathways that may be involved in the growth of RB1-depleted cancer cells." (PMID 34404904, 2021). "RB1 is a tumor suppressor gene that is inactivated in a significant proportion of all cancer cases." (PMID 33591981, 2021). "Taken together, the co-expression of these genes (NCOA6, HDAC1, RB1) could play a role in various types of cancer." (PMID 34439147, 2021).
cancer (continued). "Irreversible dysfunction of RB1 often predicts poor prognosis in many types of cancer." (PMID 34359636, 2021). "In addition to germline pathogenic variants in RB1, five of 42 patients (12.0%) consented for germline MSK-IMPACT testing had pathogenic or likely pathogenic germline mutations in non-RB1 cancer predisposition genes." (PMID 33466343, 2021). "RB1 deficient cells can have overexpression of HIF-1α and aid cancer cells in evading apoptosis." (PMID 34531756, 2021). "In addition, some cancer types, such as RB1-deficient breast cancers, KRAS-driven cancers, and chemoresistant melanoma, are particularly reliant on OXPHOS activity and are especially sensitive to OXPHOS inhibition." (PMID 34827664, 2021). "Therefore, modulating EMT to inhibit the cell stemness was the reason why Rb1 or CK enhanced the sensitivity of cancer cells to chemotherapeutic agents." (PMID 34975466, 2021). "The patient-derived iPSC-RBs showed inactivation of the 2nd allele of the RB1 gene and no other mutations in known cancer genes." (PMID 34315877, 2021). "Taken together, in addition to targeting aberrant cell cycle progression, functional suppression of the proteins aberrantly expressed as a result of RB1 inactivation may also be beneficial in cancer treatment." (PMID 34359636, 2021). "This suggests that RB1 may in fact be involved in the initiation and/or progression of previously unexpected varieties of cancer." (PMID 34359636, 2021). "We note that analysis of potential SL partners in human cancer cell lines revealed that the top 10 most responsive RB1-deficient human cancer cell lines for different hits were not from the same types of tumors." (PMID 33591981, 2021). "A report suggested that M2I-1 sensitizes cancer cells to anti-mitotic reagents but, thus far, no report has tested its efficacy in RB1-deficient context." (PMID 34359636, 2021). "The lack of evidence for frank HRd in cancer cell lines with RB1 loss raises questions as to the mechanism that underlies their inhibitor sensitivity." (PMID 34862364, 2021). "As almost all human cancers carry abnormalities in the pRB/E2F pathway components including INK4A, CCND, CDK4/6, RB1, or E2Fs, genetic of functional inactivation of the pRB/E2F pathway seems to be indispensable for deregulated proliferation in most cancer settings." (PMID 33003565, 2020). "Therefore, we aimed to detect the expression of miR-215 in cancer tissues and adjacent healthy tissues, and to explore the effects of miR-215 expression regulation on Rb1 expression through the transfection with miR-215 mimics and inhibitors." (PMID 33083296, 2020). "Most of the mutations of MET, TSC2, and RB1 that were detected in cohort 1 of this study were private and would therefore not qualify for a broadly applicable “off-the-shelf” cancer vaccine or ACT approach." (PMID 32228647, 2020). "GE5, GE50 and Rb1 are conducive to relieving the cancer cachexia symptom of systemic inflammation." (PMID 32020864, 2020). "CDK4/6–phosphorylated RB1 has been shown to promote anticancer immunity by inhibiting nuclear factor-κB activation and programmed death-ligand 1 expression, further indicating the immunological relevance of palbociclib during cancer treatment." (PMID 33282875, 2020). "This analysis sheds new light on genetic/gene expression interactions, how cell cycle regulatory networks related to RB1 impact clinical outcomes, and has defined unique interactions that could represent new vulnerabilities for the treatment of cancer." (PMID 32242058, 2020).
cancer (continued). "Because we found that GE5 and GE50 (Rg1: 3.49%, Re: 8.6%, Rf: 1.46%, Rb1: 14%, Rc: 16.4%, Rb2: 11.69%, and Rd.: 9.5%) have an improved effect on two inflammatory cytokines in a cancer cachexia mouse model, it is important to determine which compound played the major role." (PMID 32020864, 2020). "Currently, although it is widely accepted that mutations in the 2 alleles of the RB tumour suppressor gene RB1 are triggers for this cancer, the underlying mechanisms of RB progression are not fully understood." (PMID 33090698, 2020). "Similarly, RB1-E2F is necessary for cancer cell growth, migration, self-renewal differentiation, and so on." (PMID 32850350, 2020). "Additional studies provided structural evidence for the RB1 gene as the prototypic recessive human cancer gene, supporting Knudson’s hypothesis." (PMID 31683923, 2019). "When compared with Rb1, CK has significantly stronger anti-cancer effects." (PMID 31426477, 2019). "Moreover, Rbfox2 reduced RB1 protein levels under stress conditions and promoted cancer cell cycle progression and proliferation." (PMID 31028247, 2019). "Moreover, tumor suppressor gene Rb1 promoter became hypermethylated due to DNMT1 overexpression in several human cancers." (PMID 30680063, 2018). "Profiling CDK4/6 inhibitors in large-scale cancer cell line screens in vitro confirmed that RB1 loss of function is a negative predictor of sensitivity." (PMID 30443290, 2018). "RB1, a tumor suppressor gene, is normally inactivated in numerous cancers." (PMID 30680063, 2018). "But only few studies have reported the correlation between RB1 and metastasis of other cancers." (PMID 28716024, 2017). "Very few of these cancers carry mutations in the RB1 gene, and pRb, is inactivated by phosphorylation in these nonretinoblastoma cancers." (PMID 28211617, 2017). "(b) Rb1 disrupts many of the characteristic cancer promoting activities." (PMID 27825116, 2017). "pRB, which is encoded by RB1 gene, is one of the most commonly mutated genes in cancer." (PMID 28931650, 2017). "It is unlikely that non-cycling cells acquire two RB1 mutations, suggesting both a difference between the familial and the non-hereditary forms and an increased probability to initiate the cancer from a cycling progenitor." (PMID 29124525, 2017). "It is puzzling why children with heritable RB1 mutations develop tumors in the retina but no other types of cancer at a young age." (PMID 29124525, 2017). "We sought to characterize how RB1 can provide clues to understanding the pathological properties of these two diseases that seem to show distinct behaviours (with highly proliferative properties in cancer and degenerative properties in AD)." (PMID 26975659, 2016). "The RB1 gene was down-regulated in TKI-resistant PC-9/AB2 cells with combination treatment, therefore we hypothesized that inhibition of the pRb pathway by PD 0332991 contributes to the anti-cancer effects of gefitinib in TKI-resistant NSCLC cells." (PMID 27825114, 2016). "Therefore, RB1 phosphorylation can provide cancer cells with both proliferative and survival advantages." (PMID 26160835, 2015). "Interestingly, total levels of Rb1 dropped upon miR-10b inhibition, suggesting a feedback mechanism developed by cancer cells to maintain the levels of E2F activity." (PMID 25738367, 2015). "Here, we provide an overview of the main findings on the function of RB1 and the other family members in the apoptotic process and in the coordinated control of cell death and proliferation in both normal cells and preclinical cancer models." (PMID 26160835, 2015).